SLC26A4 (solute carrier family 26 member 4)
Diseases named in the same sentence as SLC26A4 in open-access papers (continued):
Sharing a sentence is not in itself a finding about the gene and the disease.
hearing loss (continued). "SLC26A4-associated hearing loss is associated with inner ear malformations, hearing loss, vestibular dysfunction, and thyroid abnormalities." (PMID 37928735, 2023). "In non-syndromic hearing loss patients, p.L445W and p.M147T mutations in SLC26A4,followed by cell experiments, proved that the mutation prevented pendrin from targeting to the plasma membrane." (PMID 36072472, 2022). "Both Pendred syndrome (PS) and nonsyndromic hearing loss with an enlarged vestibular aqueduct (EVA) are autosomal recessive disorders caused by SLC26A4 pathogenic variants." (PMID 35207372, 2022). "Mutations in SLC26A4 are the second most frequent cause of hereditary hearing loss in human, after GJB2 gene mutations." (PMID 36072472, 2022). "Homozygosity for SLC26A4 c.349C>T, p.L117F has also been observed in four other Ashkenazi families during screening for childhood hearing loss by genetic clinics in Israel." (PMID 36233414, 2022). "Screening pathogenic variants in the SLC26A4 gene is an important part of molecular genetic testing for hearing loss (HL) since they are one of the common causes of hereditary HL in many populations." (PMID 36362242, 2022). "The present study elucidated the possible mechanism and provides novel therapeutic strategy for hearing loss due to mutations in SLC26A4." (PMID 36072472, 2022). "In general, SLC26A4 mutations give rise to hearing loss, which is more pronounced at high frequency." (PMID 35249537, 2022). "In the present study, we intended to investigate the relationship between SLC26A4 mutations and hearing loss and to further clarify the possible underlying mechanism." (PMID 36072472, 2022). "In the present study, three recombinant plasmids with different SLC26A4 mutants (c.85G>A, c.2006A>T, and c.853G>A) were generated to investigate the underlying mechanism of SLC26A4 mutations in hearing loss." (PMID 36072472, 2022). "SLC26A4 is another common gene causing nonsyndromic hearing impairment with enlarged vestibular aqueducts in Asian and Middle Eastern populations and Ashkenazi Jews8." (PMID 33597575, 2021). "Hearing loss due to SLC26A4 has been reported as third most common cause of hearing loss in a study in a pan-ethnic population." (PMID 33138774, 2020). "Variants in the SLC26A4 gene are correlated with nonsyndromic hearing loss with an enlarged vestibular aqueduct (EVA)." (PMID 32770655, 2020). "The novel finding enriches the mutant spectrum of the SLC26A4 gene and provides a basis for genetic counseling and diagnosis of hearing loss with EVA." (PMID 32770655, 2020). "Consistent with previous publications, GJB2 and SLC26A4 were the major genetic causes of hearing loss in the Chinese population; the main contributing variants were GJB2 c.235delC, GJB2 c.109G > A, and SLC26A4 c.919-2A > G." (PMID 31138263, 2019). "For example, the Hearing Loss VCEP classified the SLC26A4 variant c.349C>T as pathogenic (and later downgraded the variant to likely pathogenic), despite also applying BS3_supporting criteria to the variant." (PMID 31783775, 2019). "Our study suggests that gene therapy for hearing loss caused by SLC26A4 mutations in human patients is feasible, however, ethical concerns should prevent a direct translation, since local gene delivery amounts to an invasive procedure for a non-lethal disease." (PMID 31695761, 2019). "A total of 155 patients with bilateral hearing loss carrying SLC26A4 gene mutations were further subjected to high-resolution temporal bone CT and thyroid B ultrasound tests." (PMID 30842343, 2019). "Mutations in the SLC26A4 gene, which encodes the anion exchanger pendrin, are worldwide the second most prevalent cause of hereditary hearing loss; the most prevalent causes are mutations of GJB21." (PMID 31695761, 2019). "It is possible there are pathogenic variants in regions or genes unlinked to SLC26A4 that cause hearing loss and nonsyndromic EVA or modify the severity of hearing loss in ears with EVA." (PMID 31266487, 2019).
hearing loss (continued). "Mutations in the SLC26A4 gene are reported to be the most frequent cause of hereditary hearing loss in East Asia, and the second most common cause worldwide, after Connexin 26 (GJB2) gene mutations." (PMID 29739340, 2018). "In our study, probably causative mutations in SLC26A4 were found in 3% (2/68) of the pedigrees presenting autosomal recessive non-syndromic hearing loss." (PMID 29739340, 2018). "We therefore present the analysis of the SLC26A4 gene in a cohort of nineteen Austrian patients with hearing loss, 18 of whom have unilateral or bilateral EVA and one has bilateral agenesis of the vestibular aqueduct." (PMID 29320412, 2018). "The purpose of our study was to investigate the contribution of SLC26A4 mutations to hearing loss in Brazilian patients." (PMID 29739340, 2018). "Mutations of SLC26A4 are a common cause of hearing loss associated with enlargement of the endolymphatic sac (EES)." (PMID 28994389, 2017). "Of the 28 children, 12 exhibited EVA and/or Mondini’s deformity (cochlear anomaly where the cochlea has only 1.5 turns), representing DFNB4 hearing impairment with bi-allelic mutations in SLC26A4." (PMID 28383030, 2017). "Given that the frequency of SLC26A4 mutations in Korean patients with EVA is >90%, it is reasonable to perform TBCT for discriminating between patients with hearing loss due to SLC26A4 mutations and those with NSHL due to other AR mutations." (PMID 28383030, 2017). "The SLC26A4 mutation leads to the development of a variable clinical spectrum of hearing loss due to inner-ear malformation as an EVA or mondini cochlea associated with goiter and in some cases CH." (PMID 26886089, 2016). "There were 45 (13.27%) patients who were confirmed to have inherited hearing loss because they carried two SLC26A4 pathogenic mutations: fourteen homozygotes (13 c." (PMID 27247933, 2016). "Nonsyndromic enlargement of vestibular aqueduct (NSEVA) is an autosomal recessive hearing loss associated with mutations in the anion transporter SLC26A4, which encodes the anion transporter protein pendrin." (PMID 25372295, 2014). "In China, almost 50% of patients with nonsyndromic hearing loss carry the GJB2 or SLC26A4 mutations." (PMID 24337325, 2014). "With regard to studies, DFNB4 locus (SLC26A4) can be classified as the second cause of hearing loss." (PMID 25317404, 2014). "In China, NSEVA accounts for 20–25% of hereditary hearing loss cases, and biallelic mutations in SLC26A4 represent nearly 90% of the genetic etiology of NSEVA." (PMID 25372295, 2014). "So, this study aimed to determine the contribution of this locus in hearing loss as well as the frequency of SLC26A4 gene mutations in a population in the west of Iran." (PMID 25317404, 2014). "No homozygous or compound heterozygous mutation of the GJB2 or SLC26A4 gene was found, and the mitochondrial m.1555A > G homogeneous mutation were responsible for hearing loss in 1.75% of 114 Tibetan patients." (PMID 24612839, 2014). "The TECTA gene is known as a causative gene for DFNA8/DFNA12 and DFNB21 hearing loss in humans, and SLC26A4 is related to autosomal recessive hearing loss." (PMID 25008054, 2014). "Mutations of SLC26A4 are the most common cause for EVA-associated hearing loss that can either be non-syndromic (DFNB4; OMIM # 600791) or syndromic with enlargement of the thyroid gland (Pendred syndrome; OMIM #274600)." (PMID 23874234, 2013). "We also considered the mutations in the GJB2, GJB6 and SLC26A4 genes which are recognised to be among the most frequent causes of hearing impairment." (PMID 23969527, 2013). "GJB2 mutations are the most common cause of childhood hearing loss worldwide, followed by SLC26A4 mutations." (PMID 24164807, 2013). "Mutations of SLC26A4 are a common cause of human hearing loss associated with enlargement of the vestibular aqueduct." (PMID 23874234, 2013). "This suggests that heterozygosity for SLC26A4 mutations is important in the aetiology of the hearing loss in these patients." (PMID 23965030, 2013).
hearing loss (continued). "Pendred syndrome (PS) and nonsyndromic hearing loss associated with enlarged vestibular aqueduct (EVA) are caused by SLC26A4 mutations." (PMID 23705809, 2013). "Of the 342 hearing loss patients with mutations or variants in SLC26A4, 320 were examined by temporal CT scan or MRI." (PMID 23185506, 2012). "The progress made in research on hereditary hearing loss indicates the importance of molecular diagnosis using the SLC26A4 gene in patients with hearing loss." (PMID 23151025, 2012). "To investigate the incidence of EVA in Chinese hearing loss populations and provide appropriate genetic testing and counseling to patients with SLC26A4 variants, we conducted a large-scale molecular epidemiological survey of SLC26A4 in China." (PMID 23185506, 2012). "Because 97.9% of Chinese patients with EVA carry an SLC26A4 mutation, SLC26A4 mutations in hearing loss patients indicate a high possibility of EVA." (PMID 23185506, 2012). "SLC26A4 mutations were detected in nearly 15% of 2352 non-syndromic Chinese hearing impairment patients, with IVS7-2A>G being the most prevalent." (PMID 23185506, 2012). "Molecular epidemiology surveys showed that there are more than 100 SLC26A4 variants in the Chinese hearing loss population, of which at least half are novel." (PMID 23185506, 2012). "In typical areas of China, GJB2 gene mutations account for the etiology in about 18.31% of patients with hearing loss, SLC26A4 mutations account for about 13.73%, and the 12S rRNA A1555G mutation accounts for 1.76%." (PMID 22389666, 2012). "Few large-scale molecular epidemiological surveys on the SLC26A4 gene in hearing loss populations have been reported." (PMID 23185506, 2012). "Mutations in SLC26A4 cause Pendred syndrome (hearing loss with goiter) or DFNB4 (non-syndromic hearing loss with inner ear malformation, such as enlarged vestibular aqueduct or Mondini deformity)." (PMID 21961810, 2011). "After the systematic comparison of various genes in different countries or ethnic differences between the mutation frequencies, we calculated the average frequency of GJB2, GJB3, GJB6, SLC26A4 and mtDNA mutations in patients with nonsyndromic hearing loss." (PMID 23554706, 2011). "Recessive mutations in the SLC26A4 gene are a common cause of hereditary hearing impairment worldwide." (PMID 21811566, 2011). "Recent studies have provided excellent insights into how SLC26A4 mutations lead to hearing impairment." (PMID 21811566, 2011). "DNA sequence analysis for SLC26A4 mutations was performed in 144 patients with sensorineural hearing loss in this study." (PMID 21961810, 2011). "The GJB2 gene accounted for the etiology in about 18.31% of the patients with hearing loss, SLC26A4 accounted for about 13.73%, and mtDNA 1555A>G mutation accounted for 1.76%." (PMID 19744334, 2009). "Almost 50% of the patients with nonsyndromic hearing loss in these typical Chinese areas carried GJB2 or SLC26A4 mutations." (PMID 19744334, 2009). "Mutations in the GJB2 gene accounted for 18.31% of the patients with nonsyndromic hearing loss, 1555A>G mutation in mitochondrial DNA accounted for 1.76%, and SLC26A4 mutations accounted for 13.73%." (PMID 19744334, 2009). "Sequence analysis of the SLC26A4 gene in these 227 patients with hearing impairment identified 28 patients with two confirmed pathogenic mutations and one compound heterozygote for two unclassified variants, Y375C and R470H, which are most likely pathogenic." (PMID 19744334, 2009). "It was employed for multiplex detection of 11 mutations in GJB2, GJB3, SLC26A4 and mitochondrial DNA causing hereditary hearing loss." (PMID 19366456, 2009). "In this study, we found that SLC26A4 mutations were detected in nearly 20% of our patients with hearing impairment with IVS7-2A>G being the most prevalent mutation." (PMID 19040761, 2008). "In Inner Mongolia, China, mutations in SLC26A4 gene account for at least 12.6% (17/135) of the patients with nonsyndromic hearing loss." (PMID 19040761, 2008).
hearing loss (continued). "Since 97.9% of Chinese EVA patients carry SLC26A4 mutation, SLC26A4 mutation in hearing loss patients indicates a high possibility of EVA." (PMID 19040761, 2008). "In Inner Mongolia, China, mutations in SLC26A4 gene account for about 12.6% (17/135) of the patients with hearing loss." (PMID 19040761, 2008). "Taken together, these future directions may help overcome the intrinsic limitations at this locus and improve the feasibility of therapeutic genome editing for SLC26A4-related hearing loss." (PMID 40507794, 2025). "Moreover, we have successfully established a robust iPSCs disease model, which provides a solid foundation for future comprehensive investigations into the role of the SLC26A4 gene in hereditary hearing loss." (PMID 40260864, 2025). "SLC26A4 is the second most common cause of hereditary hearing loss worldwide." (PMID 40260864, 2025). "The SLC26A4 gene is one of the key genes involved in the etiology of hearing loss." (PMID 41226768, 2025). "Children with known variants of GJB2 and SLC26A4 were identified from 485 children with hearing loss who underwent testing with Next Generation Sequencing (NGS) between January 2015 and February 2018, prior to expanded screening for genetic variants and congenital CMV." (PMID 40008839, 2025). "Numerous studies have aimed to elucidate these genotype–phenotype correlations in patients with identified biallelic pathogenic SLC26A4 variants, as well as to investigate the mechanisms of hearing loss in cases where only a single pathogenic SLC26A4 variant is detected." (PMID 41226768, 2025). "The aim of this study was to assess the added benefit of newborn genetic screening for GJB2 and SLC26A4 variants in conjunction with newborn hearing screening in a large cohort of children followed for hearing loss at a Canadian pediatric tertiary healthcare center." (PMID 40008839, 2025). "We hypothesized that abnormalities of PDCs and their interacting partners are the primary causes of SLC26A4-related hearing loss." (PMID 37322474, 2023). "Thus, the presence of SLC26A4 should be investigated in all individuals with sensorineural hearing loss and inner ear malformations." (PMID 36529647, 2022). "More than 120 genes participate in hearing loss, including SLC26A4 gene." (PMID 36072472, 2022). "Recessive variants of the SLC26A4 gene are globally a common cause of hearing impairment." (PMID 33801843, 2021). "Recessive variants of the SLC26A4 gene are an important cause of hereditary hearing impairment." (PMID 34697379, 2021). "Although GJB2 and SLC26A4 mutations account for a large part of causes of hereditary deafness, there are still a large number of known or unknown gene mutations that cause hearing loss." (PMID 34335733, 2021). "Mutations in the SLC26A4 gene are known to be responsible for a wide phenotypic spectrum, ranging from Pendred syndrome (a disorder associated with sensorineural hearing loss and thyroid goiters) to non‐syndromic hearing loss with enlarged vestibular aqueducts (EVA) (DFNB4)." (PMID 32027099, 2020). "Therefore, in cases that manifest hearing loss, especially congenital sensorineural hearing loss associated with malformations of the inner ear, SLC26A4 variants and their possible clinical implications must be considered in the molecular work-up." (PMID 29320412, 2018). "In addition, the causal relation between sequence alterations in the SLC26A4 gene and hereditary hearing loss is firmly established." (PMID 29320412, 2018). "Interestingly, the frequency of SLC26A4 mutations in subjects with sporadic congenital hearing loss in the present study is higher compared that reported in previous studies." (PMID 28383030, 2017). "SLC26A4 pathogenic variants were identified in 7 % of patients with positive diagnoses; however, all of these patients had severe-to-profound hearing loss (10 % of severe-to-profound hearing loss)." (PMID 26969326, 2016).
hearing loss (continued). "As the major genetic contributor to nonsyndromic SNHL, PS, and EVA, SLC26A4 might be the second most frequent causative gene of hereditary hearing loss worldwide." (PMID 27018795, 2016). "According to genetic detections of GJB2, SLC26A4, and mtDNA12SrRNA via the SNPscan assay, the fact that almost half of the patients with nonsyndromic hearing loss appeared to have a genetic etiology shows that the SNPscan assay is an available diagnosis tool for studies on genetic hearing loss." (PMID 27247933, 2016). "Thus, the molecular etiology of hearing loss associated with SLC26A4 mutations, as well as the genotype-phenotype correlation, was still needed to be further investigated." (PMID 26035154, 2015). "As a consequence, patients with SLC26A4 mutations might acquire more hearing experiences before implantation than those with congenital hearing loss." (PMID 26397989, 2015). "Mutations in the SLC26A4 gene are a common cause of human hereditary hearing impairment worldwide." (PMID 23755160, 2014). "In addition, Pendred syndrome mutations in SLC26A4 account for 10% of hereditary hearing loss in most world populations." (PMID 24337325, 2014). "The GJB2, MT-RNR1, and SLC26A4 genes have been reported as common causative genes of hearing loss in the Korean population and some mutations of these genes are the most common mutations associated with hearing loss." (PMID 23469187, 2013). "Thus, mutations in SLC26A4 were identified in 9.97% (23/235) of patients with hearing impairment in this study." (PMID 24341454, 2013). "A definite etiologic diagnosis could be made using molecular diagnostics in individuals with concomitant hearing impairment and biallelic SLC26A4 mutations." (PMID 23151025, 2012). "However, the test evaluates only few major genes, such as GJB2, SLC26A4 and mitochondrial genes, and is unable to detect other genetic causes of hereditary hearing loss." (PMID 22938506, 2012). "Novel SLC26A4 variants found in Chinese hearing loss population." (PMID 23185506, 2012). "Genotypes and phenotype of SLC26A4 gene in Tibetan patients with hearing loss." (PMID 22389666, 2012). "SLC26A4 mutation accounts for almost fifteen percent causative factors of hearing loss." (PMID 23554706, 2011). "The hearing impairment in our MD group might have been caused by factors other than the SLC26A4 gene in our Chinese population." (PMID 21961810, 2011). "Moreover, among the recessive hereditary hearing loss genes, the high prevalence genes of GJB2 or SLC26A4 also can be found only one mutant allele in the congenital hearing loss or enlarged vestibular aqueduct syndrome patients." (PMID 20504331, 2010). "Thus, mutations in SLC26A4 were identified in 18.66% (53/284) of patients with hearing impairment in typical areas of China, 29 with two mutant alleles and 24 with one mutant allele." (PMID 19744334, 2009). "Park and Pryor observed that patients with PS were always associated with two mutant alleles in SLC26A4 consistent with autosomal recessive disorder, whereas patients with nonsyndromic hearing loss and EVA might have one or zero mutant allele." (PMID 19040761, 2008). "Thus, mutations in SLC26A4 were identified in 19.26% (26/135) patients with hearing impairment in Inner Mongolia, China, 17 with two mutant alleles and 9 with one mutant allele." (PMID 19040761, 2008). "Analysis of the SLC26A4 gene, conducted during long-termstudies of inherited hearing loss in Tuvinians, the indigenouspopulation of the Tyva Republic (Southern Siberia), showedthat the proportion of SLC26A4-associated hearing loss inTuvinian patients is one of the highest in the world (28.2 %)." (PMID 40144368, 2025). "However, some variants might lead to the progression of hearing loss, and some SLC26A4 genotypes may be associated with a normal thyroid phenotype and less severe hearing loss." (PMID 33801843, 2021).